CMC2 (C-X9-C motif containing 2)
Description:
May be involved in cytochrome c oxidase biogenesis.
Synonyms: C16orf61; DC13; MGC45036; 2310061C15Rik
Tractability: PROTAC: ubiquitination databases record sites on it.
Gene: Protein-coding gene on chromosome 16 (80,966,448 to 81,020,270, reverse strand). Ensembl gene ENSG00000103121.
Subcellular location: Mitochondrion
Subcellular location (Human Protein Atlas): Mitochondria; Cytosol
Pathways (Reactome):
Protein localization: Mitochondrial protein import
Gene Ontology:
Molecular function: protein binding
Cellular component: mitochondrion
Homologues: Orthologues: rabbit CMC2 (85% identical), mouse Cmc2 (82% identical), guinea pig CMC2 (78% identical), chimpanzee CMC2 (70% identical), zebrafish cmc2 (59% identical), tropical clawed frog cmc2 (54% identical), Drosophila melanogaster CG42375 (39% identical), Caenorhabditis elegans C35D10.17 (37% identical).
Diseases named in the same sentence as CMC2 in open-access papers:
CMC2 is named in the same sentence as 13 diseases in open-access papers, as found by Europe PMC text mining. Sharing a sentence is not in itself a finding about the gene and the disease. The quoted sentences say what the papers report.
epilepsy (1 paper, 2025). A brain disorder characterized by episodes of abnormally increased neuronal discharge resulting in transient episodes of sensory or motor neurological dysfunction, or psychic dysfunction. "There were 8 proteins shared between epilepsy and ischemic stroke: SH3BGRL3, BPNT1, PTPMT1, PACSIN3, MIPEP, CMC2, ABCA5, and PTK2B." (PMID 40624693, 2025).
leukemia (1 paper, 2021). A malignant (clonal) hematologic disorder, involving hematopoietic stem cells and characterized by the presence of primitive or atypical myeloid or lymphoid cells in the bone marrow and the blood. "In addition, we identified genes of previously unknown cancer relevance with regards to leukemia circulation (e.g., LRIF1, DNAJC1, and CMC2) and therapeutic treatment (e.g., EBPL, MESDC2, ZRANB2, GTF2A2)." (PMID 34764253, 2021).
uterine cancer (1 paper, 2025). Primary or metastatic malignant neoplasm involving the uterine corpus and/or the cervix. "The ‘Genotype’ hypothesis findings for uterine cancer showed that the expression of the genes CMC2, CXCL13, CXCL19, LAG3, SRD5A2, and others had changed." (PMID 40847033, 2025).
CMC2 also shares sentences with these, for which no sentence is quoted: malaria (13 papers); cerebral malaria (6); cancer (1); dyslipidemia (1); infection (1); ischemic stroke (1); metastatic melanoma (1); retinopathy (1); Thrombocytopenia (1); tumor (1).